OGT (O-linked N-acetylglucosamine (GlcNAc) transferase)
Diseases named in the same sentence as OGT in open-access papers (continued):
Sharing a sentence is not in itself a finding about the gene and the disease.
cervical carcinoma (continued). "Previous research supports this hypothesis that the KRAS/ERK signaling pathway is closely related to OGT levels in pancreatic, gastric, and cervical cancers." (PMID 35387659, 2022). "Notably, in irradiated HeLa cervical cancer cells, OGT O-GlcNAcylates H2AX at Ser139 and Mediator of DNA Damage Checkpoint 1 (MDC1), and restrains the expansion of the DSBs-induced phosphorylation from the DNA damage sites." (PMID 36059648, 2022). "OGT upregulation in cervical cancer was shown to be related to worse prognosis." (PMID 31781477, 2019). "Therefore, we examined expression of O-GlcNAcylation and OGT in HeLa, Caski, and C33A cervical cancer cell lines." (PMID 29435130, 2018). "Moreover, depleting OGT levels with OGT-specific shRNA significantly reduced levels of HCF-1 in HeLa cervical cancer cells as shown by western blot analysis (P < 0.0001), supporting a role for OGT in stabilizing HCF-1 protein." (PMID 27331873, 2016). "Because HCF-1 is stabilized by O-GlcNAcylation, and a transcription co-factor involved in oncogenic viral reactivation processes, playing a critical role in tumor formation, we tested the effects of OGT overexpression on HCF-1 in HeLa cervical cancer cells transfected with Flag or Flag-OGT." (PMID 27331873, 2016). "The OGT targeting in cervical cancer cell might be of therapeutic value." (PMID 34485140, 2021). "Moreover, OGT depletion reduced proliferation, invasion, and metastasis in cervical cancer cells." (PMID 27331873, 2016). "Knockdown of O-GlcNAc transferase (OGT) or ST6GAL1 suppresses tumorigenesis and metastasis of HPV18+ cervical cancer Hela cells." (PMID 34745942, 2021). "It was also found OGT expression would enhance the expression levels of HPV E6 and E7 proteins in cervical cancer cells, so it seems E6 and OGT are in a feedforward cycle to enhance each other’s activity." (PMID 34638625, 2021). "Taken together, these findings suggest that OGT, O-GlcNAcylated LXRs, and SREBP-1 increase sCLU expression in cervical cancer cells, which contributes to drug resistance." (PMID 29435130, 2018). "Immunoprecipitation assays showed that the interaction between OGT and HCF-1 was greatly increased in cervical cancer tissues compared to normal cervical tissues (P <0.0005 or P<0.005)." (PMID 27331873, 2016). "Global O-GlcNAc and OGT levels were increased in HeLa and SiHa HPV-positive cervical cancer cell lines compared to C33A and HaCaT HPV-negative cell lines (P <0.05)." (PMID 27331873, 2016). "Because depleting OGT with shRNA affects E6 and E7 protein expression in cervical cancer cells, and cervical carcinogenic mechanism mainly depends on the expression of E6 and E7, we hypothesized that OGT depletion may affect cell proliferation and metastasis in cervical cancer." (PMID 27331873, 2016). "Further, high glucose enhanced the interaction between OGT and HCF-1, paralleling increased levels of E6 and E7 in cervical cancer cells." (PMID 27331873, 2016). "We found that levels of O-GlcNAc and OGT were significantly elevated in HPV16/18-positive E6- and E7-expressing cervical cancer tissues compared to normal cervical tissues (P < 0.0001 and P < 0.005, respectively)." (PMID 27331873, 2016). "Double immunofluorescence staining of OGT and HCF-1 revealed co-localization of OGT and HCF-1 in the nuclear region of cervical cancer tissues." (PMID 27331873, 2016). "We altered the O-GlcNAc levels of SH-SY5Y neuroblastoma, HeLa cervical carcinoma, and K562 leukemia cells with TMG and measured O-GlcNAc, OGT, and OGA levels at various time points up to 48 h of TMG treatment." (PMID 25520704, 2014). "Moreover, OGT deletion suppressed invasion, metastasis, and colony formation, suggesting that O-GlcNAc modification may not only regulate transcriptional processes relevant to cervical cancer, but also may affect the trafficking of cell adhesion molecules that are important to metastasis." (PMID 27331873, 2016).
cervical carcinoma (continued). "Previous studies have reported on upregulation of OGT and elevated O-GlcNAc modification in several cancers, but not in cervical cancer." (PMID 27331873, 2016). "Furthermore, we examined the interaction between OGT and HCF-1 to determine whether HCF-1 is O-GlcNAcylated in cervical cancer." (PMID 27331873, 2016). "Notably, we found that the interaction between HCF-1 and OGT, and levels of O-GlcNAcyled HCF-1 were greatly increased in HeLa cells exposed to high glucose compared to low glucose, suggesting that HCF-1 O-GlcNAcylation due to high glucose may lead to altered levels of E6/E7 in cervical cancer cells." (PMID 27331873, 2016).
pancreatic cancer (15 papers, 2014 to 2025). "Our findings demonstrate that elevated expression of METTL3 in pancreatic cancer is partially dependent on O-GlcNAcylation, which is mediated by OGT." (PMID 40495163, 2025). "Overall, our study uncovers a novel regulatory axis involving OGT-METTL3-HMGB1 that governs pancreatic cancer development and highlights the potential therapeutic strategy targeting ferroptosis and gemcitabine." (PMID 40495163, 2025). "As shown in the UALCAN database, OGT also shows a significant upregulation of protein expression in pancreatic cancer." (PMID 40495163, 2025). "In pancreatic cancer, OGT is markedly overexpressed and catalyzes O-GlcNAcylation at the S246/248 residues of Sox2, stabilizing Sox2 in the nucleus and promoting self-renewal of tumor cells." (PMID 38473392, 2024). "Genetic inhibition of OGT partially protects pancreatic cancer cells from ferroptosis induced by RSL3, another ferroptosis-inducing compound." (PMID 37838167, 2023). "On the other hand, pharmacological inhibition of OGT blocks the growth of pancreatic cancer cells with intact GLUL expression and function, suggesting a critical role of OGT and O-GlcNAc in the regulation of cancer cell growth by glutamine metabolism." (PMID 37838167, 2023). "We next investigated the endogenous protein interaction by further exploring endogenous SIRT7 and OGT in pancreatic cancer cell lines." (PMID 35422493, 2022). "Next, coimmunoprecipitation combined with subsequent MS was performed to identify O-GlcNAcylation as a potential novel PTM of SIRT7 by interaction with OGT in pancreatic cancer cell lines." (PMID 35422493, 2022). "Consistently, the PFKFB3-Ser172 phosphorylation level inversely correlated with the OGT level in pancreatic cancer patients." (PMID 32060258, 2020). "Our findings uncovered an O-GlcNAcylation mediated mechanism to promote tumor cell proliferation under metabolic stress, linking the aberrant OGT activity to tumorigenesis in pancreatic cancer." (PMID 32060258, 2020). "In vitro, OGT KO inhibits O-GlcNAcylation at the YAP1 Ser109, thereby inhibiting cell-colony formation in pancreatic cancer; in vivo, OGT knockdown downregulates tumor growth." (PMID 32390875, 2020). "Another study showed that pancreatic tumor cells with OGT knockdown injected into mice also resulted in greatly reduced tumor growth or even no tumor formation." (PMID 24918087, 2014). "Several pancreatic cancer cell lines have increased O-GlcNAc levels when compared to an immortalized control cell line; importantly, OGT protein expression was increased while OGA protein expression was decreased." (PMID 25520704, 2014). "Taken together, our study uncovers a novel aspect of NF-κB regulation, which could aid future therapeutic development by targeting O-GlcNAc transferase (OGT) in pancreatic cancer." (PMID 37835439, 2023). "OGT can be used as a potential treatment target for pancreatic cancer." (PMID 36104770, 2022). "High expression of OGT predicts poor prognosis in pancreatic cancer patients." (PMID 32060258, 2020). "OGT regulates β-catenin O-GlcNAcylation and facilitates EMT in liver, colorectal and pancreatic cancer." (PMID 39505875, 2024). "SOX2, another stem cell factor, is also directly modified by OGT in pancreatic cancer cells, which protects SOX2 from degradation and increases the self-renewing capacity of pancreatic cancer cells." (PMID 37838167, 2023). "In pancreatic cancer, ERK signaling plays a critical role in the maintenance of high OGT and O-GlcNAc levels, which is essential for cancer cell proliferation." (PMID 37838167, 2023). "In this study, we demonstrate a connection between SIRT7 and OGT, providing an unexpected link between nutrient sensor O-GlcNAcylation and H3K18 acetylation in pancreatic cancer cells." (PMID 35422493, 2022).
pancreatic cancer (continued). "To determine the clinical relevance of our finding that OGT inhibits hypoxia-induced PFKFB3-S172 phosphorylation, we performed IHC to analyze OGT and PFKFB3 pSer172 levels in 73 human pancreatic tumor specimens with validation of the antibody." (PMID 32060258, 2020). "O-GlcNAc transferase (OGT) directly induces O-GlcNAcylation at YAP1 Ser109 and Thr241, and potentiates the pro-proliferation activity of YAP1 in pancreatic cancer and liver cancer cells." (PMID 32390875, 2020). "Our results showed that inhibition of hypoxia by BAY87-2243, resulted in a decrease in OGT and GFAT1 expression in pancreatic cancer cell lines similar to that seen by Minnelide20." (PMID 28801636, 2017). "The results indicated that OGT and SIRT7 interacted in the nucleus in pancreatic tumours." (PMID 35422493, 2022). "In addition, Ma and colleagues showed that pancreatic tumor cell line PDAC, silenced for OGT display, reduced cell proliferation and anchorage-independent growth." (PMID 24918087, 2014).
X-linked intellectual disability (15 papers, 2017 to 2026). An X-linked intellectual deficiency in which not enough information is known, reported or published to indicate whether a gene causes non-syndromic or syndromic presentations. "Recently, OGT deregulation has been identified in patients with X-linked Intellectual Disability (XLID) patients, accentuating once more the importance of O-GlcNAcylation in the brain." (PMID 33479245, 2021). "Recently, variants in OGT have been shown to co-segregate with X-linked intellectual disability (XLID) in multiple families." (PMID 32080367, 2020). "Point mutations in OGT that segregate with X-linked intellectual disability have recently been described." (PMID 29588363, 2018). "Here, we report on two hemizygous mutations in OGT in individuals with X-linked intellectual disability (XLID) and dysmorphic features: one missense mutation (p.Arg284Pro) and one mutation leading to a splicing defect (c.463–6T>G)." (PMID 28584052, 2017). "However, advances in genetic screening have recently identified viable single-nucleotide variants (SNVs) in O-GlcNAc Transferase (OGT) in individuals with X-linked intellectual disability (OGT-XLID)." (PMID 42107645, 2026). "We show OGT is a dimer, providing a structural basis for how some X-linked intellectual disability mutations at the interface may contribute to disease." (PMID 34764280, 2021). "Interestingly, recent data has identified placental OGT levels as a biomarker for neurodevelopmental disorders and mutations in the OGT gene as being causative to a subset of X-linked intellectual disability (XLID) patients." (PMID 33329753, 2020). "Ongoing analysis of this disorder, OGT- X-linked intellectual disability (OGT-XLID), provides a window into how epigenetic factors linked to O-GlcNAc cycling may influence neurodevelopment." (PMID 33329753, 2020). "Genetic OGT variants identified in patients with X-linked intellectual disability (XLID) have previously been documented: first, in a clinical report, albeit accompanied by mutations in MED12 (a known XLID gene), and second, in a large screen for novel XLID genes." (PMID 28584052, 2017). "According to very recent research, X-linked intellectual disability or XLID, a type of ID caused by abnormalities in genes on the X chromosome, was found to correlate with aberrant OGT function (OGT-XLID)." (PMID 37156804, 2023). "In that sense, it was recently shown that OGT, itself, is mutated in XLID (X-linked intellectual disability)." (PMID 30400201, 2018). "Interestingly, point mutations in human OGT and MED12, another Mediator component, co-segregate in individuals affected with X-linked intellectual disability (XLID)." (PMID 29588363, 2018). "Recent studies have suggested that conservative missense mutations distal to the OGT catalytic domain lead to X-linked intellectual disability in boys, but it is not clear if this is through changes in the O-GlcNAc proteome, loss of protein–protein interactions, or misprocessing of HCF1." (PMID 31296563, 2019). "Our C. elegans electroconvulsive seizure assay was the first to model a human X-linked Intellectual Disability (XLID) associated with epilepsy and suggests a potential novel role for the OGT-1/EEL-1 complex in seizure susceptibility." (PMID 34797853, 2021).
Intellectual disability (14 papers, 2017 to 2025). "Recently, missense mutations in OGT have been linked to intellectual disability, indicating that this modification is important for the development and functioning of the nervous system." (PMID 39535175, 2024). "This link has been strengthened by discovery of O-GlcNAc transferase (OGT) missense mutations in intellectual disability." (PMID 35500025, 2022). "Missense mutations in human OGT gene, located on the X chromosome, are associated with intellectual disability (ID), a severe neurodevelopmental disorder that is characterized by impaired cognition." (PMID 35500025, 2022). "Recently, mutations in the O-GlcNAc transferase (OGT) substrate binding domain have been described that lead to intellectual disability, but the mechanisms underpinning pathogenesis remain to be explored." (PMID 31296563, 2019). "This hints at possible overlap in downstream disease mechanisms causing intellectual disability in patients bearing OGT or HCFC1 mutations." (PMID 28584052, 2017). "Additionally, cells and humans carrying inherited catalytic point mutations in OGT associated with intellectual disability are viable." (PMID 33006972, 2020). "demonstrate how the intellectual disability-associated mutation in O-GlcNAc transferase (OGT), L254F, leads not only to large shifts in OGT structure and altered dynamics in solution, but also a non-specific reduction in activity, providing the first molecular characterization of such a mutation." (PMID 29606577, 2018). "OGT missense variants leading to intellectual disability are associated with a compensatory loss of OGA mRNA and protein, leading to the intriguing possibility that the resulting impairment of pHAT domain function could also contribute to the disease mechanisms." (PMID 41044083, 2025). "OGT missense variants leading to intellectual disability are associated with a compensatory loss of OGA mRNA and protein, raising the intriguing possibility that the resulting loss of the pHAT-associated functions may also contribute to the mechanisms underpinning this disease." (PMID 41044083, 2025). "Mutations in the O-GlcNAc transferase (OGT) gene cause OGT-CDG, a neurodevelopmental disorder marked by intellectual disability and developmental delay." (PMID 41033462, 2025). "Further studies are required to define the mechanisms downstream of impaired OGT catalytic activity that affect neurodevelopment resulting in intellectual disability." (PMID 31296563, 2019). "To elucidate the potential mechanisms underlying developmental delay and defects in OGT-CDG, we focused on two recently identified mutations near the active site, N648Y and C921Y that are both associated with facial dysmorphia and intellectual disability." (PMID 41033462, 2025). "Amongst the OGT and OGA correlated genes implicated in cell cycle regulation, the gene encoding the RNA helicase DDX3X, an RNA helicase linked to S-phase entry and intellectual disability, was among the strongest OGT/OGA correlated genes (r = 0.68 and r = 0.74, respectively)." (PMID 40592469, 2025). "This establishes a potential link between OGT activity and intellectual disability." (PMID 31296563, 2019). "Recently, OGT mutations have been associated with intellectual disability, although it is not understood how they affect OGT structure and function." (PMID 29606577, 2018). "OGT-CDG is characterized by a spectrum of clinical features, with the most prominent being intellectual disability (ID) and neurodevelopmental delay, suggesting that the underlying molecular defects in OGT are critical for proper brain development and/or function." (PMID 41033462, 2025).
gastric cancer (11 papers, 2016 to 2025). A primary or metastatic malignant neoplasm involving the stomach. "Aberrant O-glycosylation, in part via OGT overexpression, is implicated in the pathology of gastric cancer." (PMID 29581850, 2018). "OGT knockdown lowers phosphorylated ERK in gastric cancers, while OGT inhibition depresses ERK1/2 signaling in cardiomyocytes." (PMID 37820866, 2023). "To investigate the function of O-GlcNAcylation in gastric cancer, we used siRNA to knock down endogenous OGT expression in SGC 7901 and AGS cell lines." (PMID 27542217, 2016). "The results showed that the OGT and O-GlcNAcylation levels were increased in all six gastric cancer cell lines compared with those in GES cells." (PMID 27542217, 2016). "Given the intricate pathogenesis of gastric cancer and the limited efficacy of current metastasis‐targeted interventions, innovative therapeutic strategies—such as circRNA‐based modulation, OGT inhibitors, and DYRK1A kinase‐targeted therapy—are urgently needed." (PMID 41117067, 2025). "This hypothesis is supported by reports showing that, in Drosophila, HepG2 cells, MCF7 cells, and recently in human gastric cancer cells, OGT activity is crucial for activating mitogen signaling pathways." (PMID 26835421, 2016). "In this study, we demonstrated that O-GlcNAc and OGT levels were increased in all six gastric cancer (GC) cell lines as compared with immortal gastric epithelial cells." (PMID 27542217, 2016). "Previous studies have observed progressively higher OGT and O-GlcNAcylation levels as gastric cancer (GC) progresses: O-GlcNAcylation and OGT levels were higher in GC with the intestinal type, higher pathological and clinical stage, and more lymph node metastasis." (PMID 36104770, 2022). "It has been recently demonstrated that the reduced O-GlcNAcylation or OGT knockdown supresses ERK1/2 activation in neutrophils and gastric cancer cells." (PMID 34943826, 2021). "Moreover, O-GlcNAcylation of RACK1 by OGT stabilizes RACK1, and results in a reduction of N-cadherin and upregulation of E-cadherin, indicating the induction of EMT and suppression of metastasis in chemoresistant gastric cancer." (PMID 33194731, 2020). "However, reducing global OGT/O-GlcNAcylation in gastric cancer cells increases PUMA and caspase-3, and further promotes cell apoptosis, suggesting that OGT is required for cell growth and survival in gastric cancer." (PMID 30082668, 2018). "Furthermore, we demonstrated that circPRELID2 significantly increased global O‐GlcNAcylation in gastric cancer cells, whereas circPRELID2‐Mut failed to do so, suggesting that circPRELID2 may also participate in OGT‐mediated O‐GlcNAcylation of additional substrates." (PMID 41117067, 2025).